NDRG2 (NDRG family member 2)
Diseases named in the same sentence as NDRG2 in open-access papers (continued):
Sharing a sentence is not in itself a finding about the gene and the disease.
prostate carcinoma (10 papers, 2016 to 2025). A carcinoma that arises from epithelial cells of the prostate gland. "Hypoxia-responsive has-mir-301a-5p and has-mir-301b-5p promoted radioresistance of prostate cancer cells via down-regulating NDRG2." (PMID 33033230, 2020). "Hypoxia-induced miR-301a/b targets the 3’UTR of Ndrg2 resulting in NDRG2 protein suppression and increased autophagy and viability of prostate cancer cells." (PMID 31138100, 2019). "The down-regulation of NDRG2 in prostate cancer tissues is significantly correlated with advanced pathological stage, positive metastatic status and high Gleason score." (PMID 26506239, 2016). "Additionally, other hypoxia response miRNAs, Mir-301a and miR-301b, were upregulated in LNCaP prostate cancer cells under hypoxic conditions, and decreased NDRG2 expression by directly targeting 3′ UTR of NDRG2." (PMID 34685629, 2021). "Similarly, as observed for NDRG1 overexpression inhibiting the expression of the E-cadherin transcriptional repressor, Slug, subsequent studies using prostate cancer cells indicated NDRG2 overexpression decreased expression of another E-cadherin repressor, Snail." (PMID 40378957, 2025). "Whether the downregulation of PD-L1 is related to increased autophagy activity by NDRG2 remains to be explored in future studies, even though decreased NDRG2 expression in prostate cancer cells revealed an increase in autophagy and cell viability and a decrease in cell apoptosis." (PMID 34885221, 2021). "Although the NDRG2 function associated with autophagy has not been well studied, downregulated NDRG2 expression contributed to increased autophagy and reduced apoptosis in prostate cancer cells under hypoxic conditions." (PMID 34685629, 2021).
bladder cancer (8 papers, 2013 to 2024). "Since NDRG2 is implicated in many aspects of tumor progression, including cell growth, cell cycle regulation, invasion and migration, it represents a promising therapeutic target for bladder cancer." (PMID 24146910, 2013). "It has been found that NDRG2 could be a good diagnostic marker for bladder cancer (AUC = 0.888)." (PMID 30544619, 2018). "NDRG2 expression was significantly lower in patients with bladder cancer compared to healthy controls." (PMID 38668066, 2024). "Overexpression of NDRG2 in bladder carcinoma cells inhibited cell proliferation, invasion, and tumorigenesis in vitro and in vivo; moreover, the expression of NDRG2 correlated negatively with the tumor grade and pathologic stage of bladder cancer." (PMID 30813460, 2019). "NDRG2 expression was significantly decreased in urine samples of patients with bladder cancer, both at mRNA and protein levels, also lower expressions were correlated with tumor grade and stage." (PMID 30544619, 2018). "NDRG2 expressions were analyzed in urine samples of 127 patients with bladder cancer and 97 healthy controls and in bladder cancer cell lines by quantitative reverse transcription-polymerase chain reaction (qRT-PCR) and Western blotting." (PMID 30544619, 2018). "We demonstrated that NDRG2 plays an important role in bladder cancer that is similar to its role in other malignant tumors." (PMID 24146910, 2013). "Meanwhile, the NDRG2 expression levels in bladder cancer cell lines (T24, 5637 and BIU-87) were lower than normal bladder cell line (SV-HUC-1)." (PMID 24146910, 2013). "In conclusion, we have demonstrated the antioncogenic role of NDRG2 in the development and invasion of bladder cancer." (PMID 24146910, 2013). "Next, we used bladder cancer cell lines as models to evaluate the effect of NDRG2 on tumor growth, differentiation and invasion in vitro and in vivo." (PMID 24146910, 2013). "The expression levels of NDRG2 in bladder carcinoma were inversely correlated with c-Myc in bladder carcinoma (r=-0.454, P<0.001)." (PMID 24146910, 2013). "MMP-2 and MMP-9 were highly expressed in bladder cancer metastasis, so the NDRG2 likely inhibited the metastasis of bladder cancer by regulating the expression of MMP-2 and MMP-9." (PMID 24146910, 2013). "Though several studies have investigated the function of NDRG2 in common tumors, there has not been functional characterization of the potential role of NDRG2 gene in bladder cancer." (PMID 24146910, 2013). "The aim of this study was to investigate the expression of NDRG2 gene in bladder cancer (BC) tissues and several bladder cancer cell lines, and to seek its clinical and pathological significance." (PMID 24146910, 2013). "Immunohistochemistry showed that NDRG2 protein positive was staining in the cytoplasm of normal tissues and bladder carcinoma." (PMID 24146910, 2013). "First, we examined the expression of NDRG2 in human bladder carcinoma tissues and compared to normal bladder tissues by immunochemistry." (PMID 24146910, 2013). "Immunohistochemistry results showed that the positive expression level of NDRG2 in bladder carcinoma tissues was significantly lower than that in normal bladder tissues." (PMID 24146910, 2013). "Therefore, the aim of the current study was to investigate the role of NDRG2 in human bladder cancer." (PMID 24146910, 2013). "The Relationship between the expression of NDRG2 and bladder carcinoma characteristics." (PMID 24146910, 2013). "The Expression of NDRG2 in normal bladder tissue and bladder carcinoma tissues." (PMID 24146910, 2013). "The expression levels of NDRG2 decreased as the degree of bladder carcinoma malignancy increased." (PMID 24146910, 2013). "Our results suggest that NDRG2 has a potential antioncogenic role in bladder cancer." (PMID 24146910, 2013).
bladder cancer (continued). "The experiments indicated that MT3 is an arsenic- and hypoxia-upregulated oncogene that promotes cell growth and invasion of bladder carcinoma cells via downregulation of NDRG1, NDRG2, and MASPIN expressions." (PMID 30813460, 2019). "Our study is the first study to demonstrate the modulations of NDRG1, NDRG2, and NDRG3 gene expressions by GDF15 in bladder carcinoma cells." (PMID 26249737, 2015). "The expressions of mammary serine protease inhibitor (MASPIN) and N-myc downstream-regulated family genes (NDRG1, NDRG2, and NDRG3) were upregulated by GDF15 overexpressions and rhGDF15 treatments in bladder carcinoma cells." (PMID 26249737, 2015). "We suspected that the expression of NDRG2 significantly suppresses the MMP-2 and MMP-9 by regulating the NF-kB signaling in the bladder cancer cells." (PMID 24146910, 2013). "The downregulation of NDRG1, NDRG2, and MASPIN gene expressions could account for the enhancement of proliferative and invasive functions of MT3 in bladder carcinoma cells." (PMID 30813460, 2019). "Our results suggest that decreased expressions of NDRG1, NDRG2, and MASPIN genes may account for the increased cell proliferation and invasiveness in bladder carcinoma cells with MT3 stably overexpressed." (PMID 30813460, 2019). "Upregulations of MASPIN, NDRG1, NDRG2, and NDRG3 expressions may account for the antitumor characteristics of GDF15 in human bladder carcinoma cells." (PMID 26249737, 2015). "The frequency of positive expression of NDRG2 in bladder carcinoma tissues was 39.17% (38/97), which was lower than that in normal bladder tissues (80%, 12/15), (χ2= 8.761, P<0.01)." (PMID 24146910, 2013).
liver cancer (7 papers, 2012 to 2022). An epithelial or non-epithelial malignant neoplasm that arises from the liver. "Collectively, these data suggest that the loss of NDRG2 in the liver microenvironment suppresses liver cancer colonies and preserves liver function." (PMID 29445150, 2018). "By establishing a liver cancer metastasis model in wild-type (WT) and Ndrg2 knockout (Ndrg2−/−) mice, we found that the loss of the tumor suppressor Ndrg2 in liver microenvironment significantly suppressed the growth of liver colonies." (PMID 29445150, 2018). "By establishing a liver metastasis model in WT and Ndrg2−/− mice, we found that loss of Ndrg2 in the microenvironment significantly inhibited liver cancer metastasis." (PMID 29445150, 2018). "However, systematic evaluation of the diagnostic and prognostic values of NDRG1 or NDRG2 expression in liver cancer is poorly investigated." (PMID 35795037, 2022). "Prognostic performance of NDRG2 on clinical prognosis in various liver cancer patient subgroups by Cox regression analysis." (PMID 35795037, 2022). "The mutation rate of NDRG1 in liver cancer reached up to 14%, and DNA methylation levels of NDRG1 and NDRG2 promoters correlated significantly with clinical prognosis." (PMID 35795037, 2022). "In the present study, we aimed to gain a better understanding of the role of NDRG2 in the tumor microenvironment during the liver cancer metastasis process, hoping to find a new therapeutic target or prognostic biomarker for this life-threatening malignancy." (PMID 29445150, 2018). "N-myc downstream regulated gene 2 (NDRG2) was recently reported as a candidate tumor suppressor in human liver cancer metastasis and it is transcriptionally reduced in HCC." (PMID 23056173, 2012). "The C-indexes and calibration plots of the nomogram suggest that NDRG1 and NDRG2 have an effective predictive performance for OS (C-index: 0.676), DSS (C-index: 0.741) and PFI (C-index: 0.630) of liver cancer patients." (PMID 35795037, 2022).
breast tumor (6 papers, 2008 to 2024). "Initially, we verified by both real-time PCR and immunohistochemistry that NDRG2 was downregulated in human breast tumor tissue, underlining recent studies showing NDRG2 expression loss in the course of tumor progression." (PMID 27400234, 2016). "Independent TCGA data sets verified a significant (P<0.001) expression loss of NDRG2 in breast tumors." (PMID 27400234, 2016). "As expected, by analyzing TCGA data we identified an inverse correlation (Pearson r = -0.548, P<0.001) of NDRG2 promoter hypermethylation and NDRG2 mRNA expression in primary breast tumors supporting CpG-hypermethylation as the molecular cause of its gene silencing." (PMID 27400234, 2016). "The results show that patients with high NDRG2 expression in breast tumour tissues had better disease-free survival than those with low NDRG2 expression (P = 0.0066 by logrank test)." (PMID 24636131, 2014). "In conclusion, we investigated whether NDRG2 expression in aggressive breast tumor cells could influence PD-L1 expression, eventually leading to an alteration of T cell proliferation in response to coculture with tumor cells." (PMID 34885221, 2021). "In the present study, we sought to investigate whether NDRG2 expression in aggressive breast tumor cells can influence PD-L1 expression, eventually leading to the alteration of T cell proliferation in response to coculture with tumor cells." (PMID 34885221, 2021). "We injected Ad-NDRG2 at the concentrations of 0.5, 1 and 2 × 109 PFU or 2 × 109 PFU Ad-LacZ every 3 days into preestablished human SK-BR-3 breast tumours (approximately 200 mm3) grown in nude mice." (PMID 24636131, 2014). "In fact, NDRG2 gene promoter was methylated in 66% of the analyzed breast tumor tissues, while in TNBC median methylation was similar to normal breast tissue methylation." (PMID 27400234, 2016). "It is also reported that NDRG2 inhibits glucose uptake and breast tumor growth by promoting GLUT1 protein degradation without affecting GLUT1 transcription." (PMID 26317652, 2015).
neuroblastoma (6 papers, 2015 to 2025). Neuroblastoma (NB) is the most common solid, extracranial childhood tumor. "These latter researchers also found in human neuroblastoma cells that the phosphorylation of tau, another hallmark of AD, was decreased after NDRG2 knockdown." (PMID 40378957, 2025). "Rong and associates (2017) discovered that using the human neuroblastoma cell line, SK-N-SH, NDRG2 modulates amyloid precursor protein (APP) processing, leading to an increase of amyloid β (Aβ) peptides via the BACE1 and GGA3 pathways." (PMID 40378957, 2025). "The ITLN1 and NDRG2 transcript levels in NB tissues were positively correlated (correlation coefficient R = 0.291, P = 0.0059), and were inversely associated with the international neuroblastoma staging system (INSS) stages." (PMID 25889839, 2015). "Recent studies have shown that knockdown of NDRG2 significantly reduces tau phosphorylation in a human neuroblastoma cell line overexpressing wild type APP695." (PMID 31947996, 2020). "NDRG2 silencing led to a decrease in Aβ1-42 (the predominant form of amyloid β found in AD) in neuroblastoma cells, and overexpression to an increase in Aβ1-42, implicating NDRG2 in the formation of senile plaques." (PMID 31485792, 2019). "In patients with neuroblastoma (n = 42), high NDRG2 expression resulted in significantly longer survival." (PMID 31485792, 2019). "NDRG2 expression was lower in neuroblastoma tissue and cells than normal dorsal ganglia and was significantly associated with the tumor suppressor intelectin 1 (ITLN1)." (PMID 31485792, 2019). "Common genes include Jagged 1 (Jag1), Tetraspanin 2 (Tspan2), neuroblastoma, suppression of tumourigenicity 1 (Nbl1) and N-myc downstream regulated gene 2 (Ndrg2)." (PMID 25545425, 2015). "In neuroblastoma cell lines and human tumors, increased ITLN1 seemed to have a PI3K/Akt-mediated protective effect by increasing the expression of N-myc downstream-regulated gene 2 (NDRG2) and by reducing tumor volume and metastatic potential." (PMID 35186726, 2022).
renal cell carcinoma (6 papers, 2010 to 2022). "Moreover, a role for NDRG2 in the oncogenic properties of renal cell carcinoma has been suggested." (PMID 22920753, 2012). "NDRG2 expression also inhibits the expression of epithelial-to-mesenchymal transition (EMT)-related genes, such as Snail, Slug, and Smad-interacting protein 1 (SIP1), and decreases EMT signaling in renal cell carcinoma." (PMID 26506239, 2016).
Alzheimer disease (5 papers, 2011 to 2025). A progressive, neurodegenerative disease characterized by loss of function and death of nerve cells in several areas of the brain leading to loss of cognitive function such as memory and language. "Increasingly, studies have shown that NDRG2 is associated with age-related disorders such as Alzheimer's disease." (PMID 31341912, 2019). "Since Alzheimer's disease is age-related, NDRG2 may also be associated with ageing." (PMID 22043305, 2011). "The critical function of NDRG2 in the nervous system was confirmed by its up-regulated expression in the brains of patients with Alzheimer's disease." (PMID 22043305, 2011). "Phosphorylation of NDRG2 at Ser350 is mediated by death-associated protein kinase 1 (DAPK1), which has been linked to neuronal cell death in multiple neurological diseases such as Alzheimer’s disease." (PMID 40378957, 2025). "However, Mitchelmore's study reported that NDRG2 up-regulation was associated with Alzheimer's disease rather than specifically associated with ageing." (PMID 22043305, 2011). "In the central nervous system, a group of studies have demonstrated that NDRG2 expression is predominantly present in GFAP-positive astrocytes in brain parenchyma under the physiological or pathological condition and in dystrophic neurons in Alzheimer’s disease." (PMID 37082656, 2023). "However, neurodegenerative diseases like Alzheimer’s disease and frontotemporal lobar degeneration might also be influenced by NDRG1 or NDRG2, although these mechanisms remain to be elucidated." (PMID 31485792, 2019).
cervical cancer (5 papers, 2012 to 2026). A primary or metastatic malignant neoplasm involving the cervix. "In the present study, the effect of cisplatin on NDRG2 expression was evaluated in human cervical cancer Hela cells." (PMID 22920753, 2012). "In the present study, we provide evidence that NDRG2 is involved in the regulation of cisplatin-resistance of cervical cancer cells." (PMID 22920753, 2012). "It will be helpful to validate the role of NDRG2 in cisplatin resistance in multiple cell lines other than Hela and to explore the clinical relevance of NDRG2 to cisplatin resistance in patients with cervical cancer." (PMID 22920753, 2012). "To further confirm whether the regulation of AMPK activity by NDRG2 overexpression is indeed associated with LKB1, we examined AMPK activation in LKB1-deficient HeLa cervical cancer cells and A549 lung adenocarcinoma cells." (PMID 25061501, 2014). "In the previous study, we have demonstrated that N-Myc downstream-regulated gene 2 (NDRG2) could promote radioresistance of cervical cancer Hela cells." (PMID 24283459, 2013). "We have found that NDRG2 expression in cervical cancer Hela cells increases significantly upon stimulation with cisplatin, the most popular chemotherapeutic agent currently used for the treatment of advanced cervical cancer." (PMID 22920753, 2012). "Considering cisplatin is often used in combination with radiotherapy for advanced cervical cancer, NDRG2 may represent a key regulator of therapy-resistance in cervical cancer cells." (PMID 22920753, 2012). "We previously reported that NDRG2 could be up-regulated by hypoxia and radiation and could promote radioresistance of human cervical cancer Hela cells." (PMID 22920753, 2012). "This led us to further explore whether NDRG2 has a role in regulation of cisplatin-sensitivity of cervical cancer cells." (PMID 22920753, 2012).
lymphoma (5 papers, 2015 to 2026). A malignant (clonal) proliferation of B- lymphocytes or T- lymphocytes which involves the lymph nodes, bone marrow and/or extranodal sites. "N-myc downstream-regulated gene 2 (NDRG2), which is a tumour suppressor, is frequently lost in many types of tumours, including adult T-cell leukaemia/lymphoma (ATL)." (PMID 38474089, 2024). "In adult T-cell leukemia/lymphoma, the reduced N-myc downstream-regulated gene 2 (NDRG2) expression suppressed the expression of PTEN mainly by activating NF-κB signaling, which resulted in the constitutive activation of PI3K/AKT signaling." (PMID 28054586, 2017). "NDRG2 is capable of activating PTEN by dephosphorylating the serine-threonine cluster, and loss of NDRG2 decreases the functionality of PTEN and subsequently activates the PI3K-Akt pathway in adult T-cell leukemia-lymphoma." (PMID 27447861, 2016). "Furthermore, p100 processing to p52 was evident in most Ndrg2-deficient lymphoma cells, suggesting that the loss of NDRG2 involves the activation of the canonical and non-canonical NF-κB signaling pathway in vivo." (PMID 26269411, 2015).